HLA-DPB2 (major histocompatibility complex, class II, DP beta 2 (pseudogene))
Synonyms: DP2B; DPB2; DPbeta2; HLA-DP2B
Gene: Transcribed unprocessed pseudogene on chromosome 6 (33,112,516 to 33,129,084, forward strand). Ensembl gene ENSG00000224557.
Diseases named in the same sentence as HLA-DPB2 in open-access papers:
HLA-DPB2 is named in the same sentence as 28 diseases in open-access papers, as found by Europe PMC text mining. Sharing a sentence is not in itself a finding about the gene and the disease. The quoted sentences say what the papers report.
cervical cancer (6 papers, 2013 to 2021). A primary or metastatic malignant neoplasm involving the cervix. "The first GWAS of cervical cancer on mostly Swedish patients with cervical intraepithelial neoplasia (CIN) III revealed that rs2516448 C/T (near MICA), rs9272143 T/C (between HLA-DRB1 and DQA1), and rs3117027C/A (at HLA-DPB2) are associated with CIN III5." (PMID 30333560, 2018). "In a genome-wide association study, we have previously identified and performed the initial replication of three novel susceptibility loci for cervical cancer: rs9272143 upstream of HLA-DRB1, rs2516448 adjacent to MHC class I polypeptide-related sequence A gene (MICA), and rs3117027 at HLA-DPB2." (PMID 24403192, 2014). "The association between HLA-DPB2 variant rs3117027 and risk of cervical cancer was not replicated in this study." (PMID 24403192, 2014). "Our results do not support previous suggestion that HLA-DPB2 variant rs3117027 is positively associated with cervical cancer." (PMID 24403192, 2014).
Autoimmunity (2 papers, 2021 to 2025). The occurrence of an immune reaction against the organism's own cells or tissues. "Of the 28 DMGs, HLA-DPB2, HLA-DRB1, PPP2R5C, and LTF were associated with autoimmunity." (PMID 34539625, 2021). "Interestingly, when |Δβ| ≥ 0.1 (simultaneously p < 0.01), 4 of the 28 DMGs—HLA-DPB2, HLA-DRB1, PPP2R5C, and LTF, which all mapped from more than one CpG site—are all associated with autoimmunity." (PMID 34539625, 2021).
hepatocellular carcinoma (1 paper, 2021). A malignant tumor that arises from hepatocytes. "Among these CpGs, DNA methylation at cg25119261 (HLA-DPB2) was reported to be differentially methylated between tumor and matched adjacent normal tissues in the context of oral squamous cell and hepatocellular cancer." (PMID 33919912, 2021).
lung carcinoma (1 paper, 2019). "The fusions HLA‐DPB2‐HLA‐DRB1 and CDH23‐HLA‐DPB1 were both annotated as lung cancer fusion in the FusionCancer database." (PMID 30903738, 2019).
tumor (7 papers, 2020 to 2022). "HLA-C, which belongs to HLA-I and can present endogenous tumor antigens to kill tumor cells effectively, was less expressed in the high-risk group, while HLA-II, such as HLA-DPB2, HLA-DQB2, HLA-DOA, and HLA-DQA2, showed an increase in the high-risk group." (PMID 35754846, 2022). "Overexpression of HLA-DPB2 promotes tumor immune infiltration by regulating HLA-DPB1, which is associated with a high survival rate in breast cancer." (PMID 36564433, 2022). "It clearly indicates that HLA-DPB2 influences the abundance of tumor-infiltrating lymphocytes in the tumor microenvironment." (PMID 34947885, 2021). "Heatmap indicated that NCF1C, HLA-DRB6, HLA-DPB2, HLA-J, HLA-H, HLA-L and RPL13AP20 displayed high expressions in the low-risk group, and thus were categorized as tumor-suppressor pseudogenes in the current study." (PMID 33378744, 2020). "The earlier discussed findings indicate that HLA-DPB2 and HLA-DPB1 take part in the tumor suppression processes of BC and that overexpression of HLA-DPB2 may predict a favorable prognosis by regulating the parent gene HLA-DPB1 expression." (PMID 32903535, 2020). "Therefore, we supposed that the HLA-DPB2/HLA-DPB1 axis might exert its roles in BC by involving an immune response in the tumor microenvironment." (PMID 32903535, 2020). "Based on literature reports and our findings, we speculate that the HLA-DPB2/HLA-DPB1 axis may convert immunologically “cold” tumors to “hot” tumors and thus exert an anticancer role in BC by recruiting T lymphocytes and NK cells into the tumor microenvironment." (PMID 32903535, 2020).
HLA-DPB2 also shares sentences with these, for which no sentence is quoted: breast carcinoma (4 papers); ovarian carcinoma (2); (CIN) III (1); asthma (1); autoimmune disease (1); B-cell lymphoma (1); breast tumor (1); cancer (1); cervical intraepithelial neoplasia (1); chronic hepatitis B infection (1); dyslipidemia (1); Hodgkins lymphoma (1); Hypertension (1); IgA nephropathy (1); infection (1); invasive breast carcinoma (1); invasive ductal breast carcinoma (1); invasive lobular breast carcinoma (1); lymphoma (1); medullary breast carcinoma (1); Sepsis (1); systemic sclerosis (1); type 1 diabetes (1).